GPR156 (G protein-coupled receptor 156)
Description:
Orphan G protein-coupled receptor involved in the regulation of hair cell orientation in mechanosensory organs of the inner ear. It is required to trigger a 180 degree reversal in hair cell orientation, creating a virtual line of polarity reversal (LPR) across which stereociliary bundles are arranged in opposite orientations.
Synonyms: GABABL; PGR28; DFNB121
Tractability: Small molecule: a structure with a bound ligand is known. Antibody: its Gene Ontology location is reachable by antibodies, with high confidence; UniProt places it where antibodies can reach, with medium confidence; UniProt predicts a signal peptide or a membrane-spanning region; the Human Protein Atlas places it where antibodies can reach.
Target class: Family C G protein-coupled receptor; Membrane receptor
Gene: Protein-coding gene on chromosome 3 (120,164,645 to 120,285,426, reverse strand). Ensembl gene ENSG00000175697.
Subcellular location: Cell membrane
Subcellular location (Human Protein Atlas): Plasma membrane
Gene Ontology:
Molecular function: protein binding; G protein-coupled GABA receptor activity; G protein-coupled receptor activity
Biological process: gamma-aminobutyric acid signaling pathway; stereocilium bundle organization; G protein-coupled receptor signaling pathway
Cellular component: plasma membrane; G protein-coupled receptor heterodimeric complex; membrane
Genetic constraint (gnomAD): Loss-of-function variants: 35 observed, 48.31 expected, observed/expected ratio (o/e) 0.72, 90% interval 0.55 to 0.96. The upper end of that interval is the gene's LOEUF score, 0.96, which puts it in group 4 of 6, group 1 being the genes least tolerant of losing a copy. Missense variants: 895 observed, 1,038.8 expected, observed/expected ratio (o/e) 0.86, 90% interval 0.81 to 0.91. Synonymous variants: 376 observed, 405.85 expected, observed/expected ratio (o/e) 0.93, 90% interval 0.85 to 1.01.
Homologues: Orthologues: chimpanzee GPR156 (99% identical), macaque GPR156 (94% identical), pig GPR156 (80% identical), rabbit GPR156 (76% identical), dog GPR156 (75% identical), guinea pig GPR156 (72% identical), rat Gpr156 (70% identical), mouse Gpr156 (70% identical), tropical clawed frog gpr156 (36% identical), zebrafish gpr156 (35% identical), Drosophila melanogaster GABA-B-R2 (15% identical), Caenorhabditis elegans gbb-2 (12% identical). Paralogues in human: GABBR2 (15% identical), GABBR1 (13% identical).
Diseases named in the same sentence as GPR156 in open-access papers:
GPR156 is named in the same sentence as 10 diseases in open-access papers, as found by Europe PMC text mining. Sharing a sentence is not in itself a finding about the gene and the disease. The quoted sentences say what the papers report.
hearing loss (4 papers, 2021 to 2025). "BeviMed identified a recessive genetic association between high-impact variants in GPR156 and the Specific Disease ‘Congenital hearing impairment’." (PMID 36928819, 2023). "Finally, we cannot exclude that GPR156 plays another role in HCs and affects their physiology, potentially also contributing to hearing loss." (PMID 34001891, 2021). "Mutations in some GPCR family proteins, such as GPR156 and GPR26, can cause hearing loss." (PMID 40248074, 2025).
Anxiety (1 paper, 2008). Intense feelings of nervousness, tension, or panic often arise in response to interpersonal stresses. "No individual effect of the four NSCS analysed was significant, however the interaction between GPR156 and DNAI2 was significantly associated (p = 0.04) with childhood depression/anxiety in this cohort." (PMID 18270580, 2008).
cancer (2 papers, 2021 to 2024). A tumor composed of atypical neoplastic, often pleomorphic cells that invade other tissues. "Furthermore, the contribution of GNRH2, PRLH, GPR156, GRIK5, LHB, and CRHR2 to the neuroactive ligand-receptor interaction pathway are specified in ATLL in consistent with some other cancers." (PMID 34446027, 2021).
tumor (1 paper, 2022). "GPR156 and PANX2 protein levels were increased in tumor tissues, consistent with their mRNA levels." (PMID 36465397, 2022).
GPR156 also shares sentences with these, for which no sentence is quoted: astrocytoma (1 paper); cavernous hemangioma (1); deafness (1); glioma (1); Hearing impairment (1); oligodendroglioma (1).